MCM6 (minichromosome maintenance complex component 6)
Description:
Acts as a component of the MCM2-7 complex (MCM complex) which is the replicative helicase essential for 'once per cell cycle' DNA replication initiation and elongation in eukaryotic cells. Core component of CDC45-MCM-GINS (CMG) helicase, the molecular machine that unwinds template DNA during replication, and around which the replisome is built. The active ATPase sites in the MCM2-7 ring are formed through the interaction surfaces of two neighboring subunits such that a critical structure of a conserved arginine finger motif is provided in trans relative to the ATP-binding site of the Walker A box of the adjacent subunit. The six ATPase active sites, however, are likely to contribute differentially to the complex helicase activity.
Synonyms: Mis5; MCG40308; P105MCM
Tractability: Small molecule: a structure with a bound ligand is known. PROTAC: ubiquitination databases record sites on it; its protein half-life has been measured.
Target class: Enzyme; Hydrolase
Gene: Protein-coding gene on chromosome 2 (135,839,626 to 135,876,479, reverse strand). Ensembl gene ENSG00000076003.
Subcellular location: Nucleus; Chromosome
Subcellular location (Human Protein Atlas): Nucleoplasm
Pathways (Reactome):
DNA Replication: Activation of the pre-replicative complex; Assembly of the pre-replicative complex; Orc1 removal from chromatin; Switching of origins to a post-replicative state; Unwinding of DNA
Cell Cycle: Activation of ATR in response to replication stress
Gene Ontology:
Molecular function: ATP hydrolysis activity; DNA helicase activity; identical protein binding; protein binding; single-stranded DNA binding; ATP binding; single-stranded 3'-5' DNA helicase activity; DNA binding
Biological process: DNA replication; double-strand break repair via break-induced replication; mitotic DNA replication; regulation of DNA-templated DNA replication initiation; DNA metabolic process; DNA replication initiation
Cellular component: chromosome; chromosome, telomeric region; CMG complex; MCM complex; nucleoplasm; nucleus
Genetic constraint (gnomAD): Loss-of-function variants: 39 observed, 75.37 expected, observed/expected ratio (o/e) 0.52, 90% interval 0.4 to 0.68. The upper end of that interval is the gene's LOEUF score, 0.68, which puts it in group 2 of 6, group 1 being the genes least tolerant of losing a copy. Missense variants: 713 observed, 857.07 expected, observed/expected ratio (o/e) 0.83, 90% interval 0.78 to 0.88. Synonymous variants: 285 observed, 301.63 expected, observed/expected ratio (o/e) 0.94, 90% interval 0.86 to 1.04.
Homologues: Orthologues: chimpanzee MCM6 (100% identical), macaque MCM6 (99% identical), pig MCM6 (98% identical), dog MCM6 (97% identical), guinea pig MCM6 (97% identical), mouse Mcm6 (96% identical), rat Mcm6 (93% identical), zebrafish mcm6 (82% identical), tropical clawed frog mcm6 (82% identical), Drosophila melanogaster Mcm6 (64% identical), Caenorhabditis elegans mcm-6 (55% identical). Paralogues in human: MCM3 (29% identical), MCM7 (27% identical), MCM5 (27% identical), MCM2 (27% identical), MCM4 (26% identical), MCM9 (25% identical), MCM8 (23% identical), MCMDC2 (12% identical).
Diseases named in the same sentence as MCM6 in open-access papers:
MCM6 is named in the same sentence as 111 diseases in open-access papers, as found by Europe PMC text mining. Sharing a sentence is not in itself a finding about the gene and the disease. The quoted sentences say what the papers report.
breast carcinoma (17 papers, 2012 to 2025). "In conclusion, MCM6 is correlated with an increased risk of breast cancer, indicating that it serves as a putative and vital regulator in breast cancer, especially in regulating its DNA replication and DNA damage response." (PMID 39477811, 2025). "Subsequently, we assessed the diagnostic potential of MCM6 in breast cancers through receiver operating characteristic (ROC) analysis." (PMID 39477811, 2025). "Larger prospective studies are warranted to further evaluate the importance of MCM6 as a diagnostic and prognostic marker for breast cancer." (PMID 35125121, 2022). "High MCM6 level is also associated with a higher histological grade in breast cancer, low-grade chondrosarcoma and endometrioid endometrial adenocarcinoma." (PMID 34993142, 2021). "This study has identified that high expression levels of MCM6 may serve as an effective early diagnostic and prognostic biomarker for breast cancer." (PMID 39477811, 2025). "Consequently, we further investigated the specific association between MCM6 and breast cancer." (PMID 39477811, 2025). "MCM6 has been shown to increase the sensitivity of breast cancer cells to PTX in a dose‐dependent manner." (PMID 39477811, 2025). "Collectively, these findings suggest that MCM6 plays a crucial role in DNA damage repair and enhances sensitivity to chemotherapy to breast cancer." (PMID 39477811, 2025). "Several countries and research institutions are concentrating on fundamental related to MCM6, while comparatively limited studied address its role in breast cancer." (PMID 39477811, 2025). "To confirm the tumour‐promoting role of MCM6, we selected the high expression of the MCM6 breast cancer cell line MCF7 based on data from the Cancer Cell Line Encyclopedia (CCLE) and HPA data sets." (PMID 39477811, 2025). "In this study, we observed that knockdown of MCM6 led to the accumulation of endogenous DNA damage due to DNA replication stress, resulting in cell apoptosis and heightened sensitivity of breast cancer cells to the chemotherapeutic drugs." (PMID 39477811, 2025). "Knockdown of MCM6 resulted in DNA replication stress and endogenous DNA damage, which induced breast cancer cells apoptosis and increased their sensitivity to chemotherapeutic agents." (PMID 39477811, 2025). "We subsequently knocked down MCM6 expression in breast cancer cells MCF7 and 4 T1 cells (The siMCM6#1 was utilized for subsequent research, hereinafter denoted as siMCM6), which resulted in suppression of cell growth in vitro." (PMID 39477811, 2025). "In summary, our study is a novel systematic analysis of MCM6 and its Kcr in regulating DNA replication stress and the DNA damage response for breast cancer treatment." (PMID 39477811, 2025). "The upregulation of MCM6 was found to have a strong correlation with leukaemia, breast cancer, male‐specific cancers, skin cancer and head and neck cancer, while also demonstrating a significant association with lactose intolerance and some symptom." (PMID 39477811, 2025). "This evidence suggests that MCM6 is likely to play a critical role in the regulation of DNA replication and the DNA damage response in breast cancer progression." (PMID 39477811, 2025). "Analysis of single‐cell sequencing data obtained from cancerSEA, indicates that MCM6 predominantly participates in DNA replication, cell cycle regulation, DNA damage repair and the DNA damage response during the progression of breast cancer." (PMID 39477811, 2025). "The results showed that breast cancer cells expressing the MCM6‐K599Q mutant (referred to as K599Q) exhibited reduced cell growth and migration compared to the CTRL and cells expressing the MCM6‐K599A mutant (referred to as CTRL and K599A, respectively)." (PMID 39477811, 2025). "The results indicated a positive correlation between PSMD14 and several ERα target genes, including GREB1, TFF1, and MCM6, in breast cancer samples." (PMID 38017133, 2024).
breast carcinoma (continued). "Upregulation of MCM6 also exists in non‐small cell lung cancer and breast cancer with worse survival and higher histological grade." (PMID 36776764, 2023). "The expression of MCM6 is positively correlated with cell proliferation, migration, invasion, and the immune response in many cancer types, such as breast cancer and lung cancer." (PMID 37454373, 2023). "Both Ki-67 and MCM6 scores were significantly varying in different molecular subtypes of breast cancer." (PMID 35125121, 2022). "Methylation of the MCM6 promoter has been reported to be an important mechanism of proliferation, invasion and migration in breast cancer cells." (PMID 34859821, 2021). "Issac MSM and his colleagues indicated that the expression of MCM2, MCM4, and MCM6 was obviously increased in breast cancer compared to that in corresponding para-cancerous tissues." (PMID 34178669, 2021). "However, a comprehensive analysis of MCM6 in the context of breast cancer has yet to be conducted in the existing literature." (PMID 39477811, 2025). "Additionally, cell proliferation and colony formation assays further confirmed that MCM6‐Kcr suppresses breast cancer cell growth due to cell cycle blockage." (PMID 39477811, 2025). "Further assays confirmed that MCM6 was crotonylated in breast cancer cells, with significantly elevated levels of MCM6‐Kcr observed following HU treatment and triggering cellular replication stress, leading to DNA damage, cell cycle arrest and suppression of breast cancer cell proliferation." (PMID 39477811, 2025). "Network pharmacology and further experiments indicated that kaempferol could inhibit breast cancer cells proliferation and induce DNA replication stress as MCM6‐knockdown and MCM6‐Kcr did." (PMID 39477811, 2025). "Furthermore, the natural product kaempferol inhibited SIRT7 expression and upregulated the MCM6‐Kcr levels, effectively improving the sensitivity of breast cancer cells to chemotherapeutic treatments." (PMID 39477811, 2025). "Additionally, TUNEL‐positive cells were identified through green fluorescence staining, revealing a substantial number of TUNEL‐positive cells in MCM6‐depleted breast cancer cells, consistent with the results from Annexin V staining." (PMID 39477811, 2025). "Additionally, we are aware of some limitations of the present study, including the fact that only limited cell lines were used to investigate MCM6 functions in breast cancers." (PMID 39477811, 2025). "Mcm3 is overexpressed in most tumors in human studies, and MCM6 expression is positively correlated with cell proliferation, migration, invasion, and immune response in numerous cancer types, including breast cancer, hepatocellular carcinoma, lung cancer, and esophageal squamous cell carcinoma." (PMID 39272991, 2024). "On the contrary, WGCNA combining with TCGA and GEO analysis identified that exceptional expression of MCM6 reflects pathologic stage of multiple tumors, serving as putative biomarkers for breast cancer, gastric cancer, renal cell carcinoma, HCC,292, 293, 294, 295 and non‐small cell lung carcinoma." (PMID 36776764, 2023). "Therefore, we compared the expression of Ki-67 and MCM6 in 124 breast cancer samples with different grades and molecular subtypes." (PMID 35125121, 2022). "Additionally, the overexpression of MCM6 is found in mantle cell lymphoma, prostate cancer, oral squamous cell carcinoma, esophageal neoplasm, renal cancer, thyroid cancer, breast cancer, endometrial cancer and prostate cancer." (PMID 30150654, 2018). "Furthermore, MCM6‐knockdown resulted in decreased cell proliferation and inhibited the DNA replication, leading to DNA replication stress and sustained DNA damage, thereby enhancing the chemotherapeutic sensitivity of breast cancer." (PMID 39477811, 2025).
breast carcinoma (continued). "In this study, we aimed to reveal whether the MCM6 expression score can be interpreted as a proliferative marker and be used as an alternative to Ki-67 in differentiating molecular subtypes and also histologic grades of breast cancer." (PMID 35125121, 2022). "Therefore, MCM6 could discriminate different histologic grades of breast cancers (P = 0.004 between grade I-II and P < 0.001 between grade II-III)." (PMID 35125121, 2022). "For instance, in breast cancer, MCM2, MCM4 and MCM6 can help distinguish breast cancers with different histological grades." (PMID 34859821, 2021). "However, the precise mechanism by which kaempferol exerts therapeutic effects in breast cancer, potentially through the modulation of SIRT7‐mediated MCM6‐Kcr, remains to be fully elucidated." (PMID 39477811, 2025). "Despite this, a comprehensive analysis of MCM6, particularly regarding its modifications in breast cancer is lacking." (PMID 39477811, 2025).
hepatocellular carcinoma (17 papers, 2018 to 2025). A malignant tumor that arises from hepatocytes. "MCM6 encodes a conserved protein, which drives S/G2 phase cell cycle progression and serves as a potential diagnostic and prognostic biomarker in hepatocellular carcinoma." (PMID 41049004, 2025). "In hepatocellular carcinoma, the knockdown of MCM6 significantly decreased proliferative and migratory and invasive capability of cancer cells in vitro, as well as decreased tumor volume, weight and the number of pulmonary metastases in vivo." (PMID 36672484, 2023). "Essentially, an existing study elucidated the significance of the mitogen-activated protein kinases/extracellular signal-regulated kinase (MEK/ERK) signaling pathway in respect to the therapeutic value of MCM6 in hepatocellular carcinoma." (PMID 33668040, 2021). "According to a previous report, MCM6 can serve as a prognostic predictor and promote metastasis in hepatocellular carcinoma (HCC)." (PMID 32175271, 2020). "MCM6 is widely considered a biomarker in several cancers, such as hepatocellular carcinoma." (PMID 34859821, 2021). "Overexpression of MCM6 is related to the diagnosis and poor prognosis of hepatocellular carcinoma." (PMID 34490114, 2021). "MCM6 may serve as potential biomarkers in patients with hepatocellular carcinoma(HCC)." (PMID 31323040, 2019). "Overexpression of MCM6 may predict the unfavorable survival outcomes of patients with glioma, hepatocellular carcinoma (HCC) and endometrioid endometrial adenocarcinoma." (PMID 38758750, 2024). "MCM6, another subunit of the MCM2-7 complex, was recently found to be up-regulated in hepatocellular carcinoma (HCC)." (PMID 33505310, 2020). "For example, MCM2, MCM5, MCM6 and MCM7 have been reported to be upregulated in cervical epithelium squamous cancers, renal cell carcinomas, hepatocellular carcinomas and esophageal squamous cell carcinomas, leading to poorer prognosis 7-10." (PMID 31528213, 2019).
cervical cancer (10 papers, 2005 to 2025). A primary or metastatic malignant neoplasm involving the cervix. "However, the higher expression of MCM2, MCM4, and MCM6 is significantly associated with favorable overall survival in cervical cancer patients." (PMID 36765810, 2023). "It is pointed out that MCM6 is abnormally expressed in a variety of malignant tumors, including liver cancer, non-small cell lung cancer, breast cancer and cervical cancer." (PMID 34233647, 2021). "Through the mining of Oncomine database and TIMER database, we found that MCM6 expression is higher in most cancers, such as sarcoma, colorectal cancer, lung cancer, cervical cancer, and liver cancer." (PMID 34233647, 2021). "Pearson correlation analysis showed that the expression of MCM3 and PRIM2 or MCM6 in cervical cancer was obviously positive (R = 0.6387 and R = 0.5443, respectively)." (PMID 34671420, 2021). "The results indicate that MCM3, PRIM2, and MCM6 could be used for early detection of cervical cancer and may be used as indicators of prognosis." (PMID 34671420, 2021). "PRIM2 and MCM6 were significantly upregulated in cervical cancer tissues by the GEPIA database." (PMID 34671420, 2021). "We selected two proteins PRIM2 and MCM6, which have strong correlation with MCM3 and have different expressions in cervical cancer compared with normal cervical tissues." (PMID 34671420, 2021). "Meanwhile, the overexpression of MCM4, MCM5, MCM6, MCM10 and RECQL4 mRNA has been reported as a poor prognostic indicator in cervical cancer." (PMID 29463213, 2018). "Our data indicates the role of MCM4, MCM5, MCM6, MCM10 and RECQL4 in the progression of cervical cancer." (PMID 23874974, 2013). "In cervical cancer, MCM2 and MCM6 are upregulated while MCM4 is downregulated." (PMID 36765810, 2023). "Hierarchical clustering and Gepia results indicated that the expression quantity of hub genes NDC80, TIPIN, MCM3, MCM6, POLA1, and PRC1 may determine the prognosis of cervical cancer." (PMID 33816217, 2021). "Interestingly, levels of members of the Minichromosome Maintenance (MCM) family (MCM2, MCM3, MCM4, MCM5, MCM6, MCM7) were found to be highly significantly increased in cervical cancer tissue from early and late stage patients as compared to healthy tissue." (PMID 29719595, 2018). "Capitalizing upon and targeting Minichromosome maintenance protein complex - specifically the MCM2, MCM4 and MCM6 subunits, ZWINT and CDC7 for experimental validation, may provide valuable insights in understanding and detection of progressing cervical neoplasia to cervical cancer at an early stage." (PMID 30150654, 2018).
melanoma (9 papers, 2008 to 2025). A malignant, usually aggressive tumor composed of atypical, neoplastic melanocytes. "In this study, we found that MCM6 expression was higher in melanoma than in normal skin in our analysis of TCGA data, and it was closely associated with T and tumor stages in patients with melanoma." (PMID 34490114, 2021). "Further immunohistochemical validation in FFPE melanomas revealed that two related genes, MCM4 and MCM6, were associated with patient MSS." (PMID 31360859, 2018). "Mcm6 is one of the mini-chromosome maintenance proteins and has been suggested as a prognostic marker in melanoma." (PMID 28212608, 2017). "Pathway analysis suggests that CDC2, CHEK1, CDC45L and MCM6 are key players in mediating the biological activity of RA in B16 melanoma cells." (PMID 18847503, 2008). "In malignant melanoma, gene expression analysis and independent immunohistochemical validation have uncovered several MCM family members, i.e. MCM3, MCM4 and MCM6 as biomarkers of poor prognosis." (PMID 22805320, 2012). "The MLV Gag protein was detected on the same level in all VLPs, while histone H3, Mcm6, Rps6 and α-tubulin were detected on lower level in VLPs without recombinant melanoma antigens (MLV Gag; first lane)." (PMID 27403717, 2016). "Furthermore, we verified key gene expression with mRNA levels after treatment with VB1 in melanoma cells, which indicated that the P21, PUMA and GADD45A expression was significantly upregulated and that the expression of MCM6, CDK1, CDK6, CYCE and CYCA was significantly downregulated." (PMID 30400954, 2018).
lung carcinoma (8 papers, 2019 to 2024). "MCM6 expression has a close correlation with histopathological grades and prognosis in endometrioid endometrial adenocarcinoma and is also implicated in the prognosis of lung cancer." (PMID 33816217, 2021). "The changes in E6AP and MCM6 at the molecular level and phenotype of lung cancer can be used to direct the early diagnosis of an active intervention in LUAD patients." (PMID 37454373, 2023). "In a study of lung cancer, the high expression of MCM6 suggests a short overall survival." (PMID 34671420, 2021). "In lung cancer, high expression levels of MCM2, MCM5, MCM6, and MCM7 could be useful prognostic markers." (PMID 31514295, 2019).